ENSG00000284946 (novel protein)
Gene: Protein-coding gene on chromosome 15 (90,966,190 to 91,022,566, reverse strand). Ensembl gene ENSG00000284946.
Genetic constraint (gnomAD): Missense variants: 696 observed, 773.23 expected, observed/expected ratio (o/e) 0.9, 90% interval 0.85 to 0.96. Synonymous variants: 266 observed, 281.24 expected, observed/expected ratio (o/e) 0.95, 90% interval 0.86 to 1.05.